DLL3 (delta like canonical Notch ligand 3)
Diseases named in the same sentence as DLL3 in open-access papers (continued):
Sharing a sentence is not in itself a finding about the gene and the disease.
scoliosis (2 papers, 2025). A congenital or acquired spinal deformity characterized by lateral curvature of the spine. "Congenital scoliosis is largely characterized by mutations in developmental genes such as TBX6, DLL3, and MESP2 and components of the Notch, Wnt, and HOX pathways." (PMID 41153437, 2025). "Phenotypically, variants in the DLL3 gene result in a short trunk, short neck, and moderate non-progressive scoliosis, while more significant scoliosis is rare in most affected individuals." (PMID 40647586, 2025).
uveal melanoma (2 papers, 2022 to 2024). A melanoma derived from melanocytes of the uveal tract. "When compared to normal uvea, UM delta-like protein 3 (DLL3) overexpression demonstrated that all of the CpGs of DLL3 were hypermethylated in uveal melanoma tissues." (PMID 39055896, 2024).
cervical cancer (1 paper, 2024). A primary or metastatic malignant neoplasm involving the cervix. "Currently, several ADC targets exist (TROP2, mesotheline, CEACAM5, DLL3, folate receptor alpha, guanylatcyclase, glycoprotein NMB, CD56, CD70 and CD138) with ADC compounds being tested in other cancer entities whose expression level in cervical cancer is of clinical interest." (PMID 38730739, 2024). "There are currently no convincing analyses of DLL3 expression in cervical cancer." (PMID 38730739, 2024).
cervical squamous cancer (1 paper, 2023). "We demonstrated that the potential oncological role of DLL3 in patients with cervical squamous cancer (CESE)." (PMID 37179118, 2023).
chronic hepatitis (1 paper, 2018). An active inflammatory process affecting the liver for more than six months. "Further studies are necessary to confirm the correlation between DLL3 expression and the pathological degree of chronic hepatitis." (PMID 29555949, 2018).
colon cancer (1 paper, 2023). "The role of other receptors and ligands on the notch pathway in colon cancer has been studied previously, but in terms of DLL3’s role in COAD development, little is known." (PMID 37274780, 2023). "In clinical sample, we identified higher DLL3 expression in colon cancer tissue than in adjacent control (p < 0.0001) and in metastasis than in primary lesion (p = 0.0056)." (PMID 37274780, 2023). "A previous microarray analysis showed that DLL3 expression did not increase with colon cancer progression, but the sample size in this study was small and it was more than a decade ago." (PMID 37274780, 2023).
colorectal adenoma (1 paper, 2020). An adenoma that arises from the colon or rectum. "We investigated mRNA expression of four Notch receptors (Notch1–4), five ligands (Jag1, Jag2, Dll1, Dll3, and Dll4), and four target genes (Hes1, Hes5, Hey1, and Hey2) using highly specific TaqMan gene expression assays in colorectal adenomas and cancers." (PMID 32211044, 2020).
Gastric NETs (1 paper, 2025). "Gastric NETs (n = 13) were mostly negative for DLL3; only one metastatic well-differentiated NET had moderate staining in 100% of the cells (H-score 200)." (PMID 40699376, 2025).
leukemia (1 paper, 2013). A malignant (clonal) hematologic disorder, involving hematopoietic stem cells and characterized by the presence of primitive or atypical myeloid or lymphoid cells in the bone marrow and the blood. "In contrast, Notch1 and Notch2 genes were un-methylated in any of the leukemia cell lines and normal controls, while DLL1, DLL3, DLL4 and Hes6 showed only low levels of methylation (9–27%) in these leukemia cell lines." (PMID 23637910, 2013).
Lewis lung carcinoma (1 paper, 2019). "Overexpression of Dll3 in Lewis lung carcinoma cells promoted cell proliferation and reduced apoptosis in vitro." (PMID 31619270, 2019).
lung carcinoid tumor (1 paper, 2021). A neuroendocrine neoplasm that arises from the lung. "The DLL3 expression has not been fully elucidated in lung carcinoid tumors." (PMID 34568063, 2021).
medullary thyroid carcinomas (1 paper, 2025). "Medullary thyroid carcinomas showed strong expression of DLL3, as previously reported." (PMID 40699376, 2025). "Both DLL3 and SEZ6 were expressed in medullary thyroid carcinomas (10 of 11 cases, H-scores 199 for DLL3 and 224 for SEZ6)." (PMID 40699376, 2025).
ocular melanoma (1 paper, 2022). A melanoma that arises from the structures of the eye or ocular adnexa. "Methylation-driven gene DLL3 could serve as a new potential diagnostic and prognostic biomarker in ocular melanoma." (PMID 36338696, 2022). "In summary, this is the first study to identify that DLL3, a methylation-driven gene, may serve as a new potential diagnostic and prognostic biomarker in ocular melanoma." (PMID 36338696, 2022). "Taken together, DLL3 may serve as a diagnostic and prognostic biomarker in ocular melanoma." (PMID 36338696, 2022). "Therefore, the methylation-driven gene DLL3 may act as a diagnostic and prognostic biomarker in ocular melanoma." (PMID 36338696, 2022). "Of note, the expression of DLL3 was upregulated in ocular melanoma tissues compared to normal melanocyte tissues (p < 0.05)." (PMID 36338696, 2022). "Considering that the results above were based on public databases, we performed immunofluorescence using biospecimens to further verify the role of DLL3 in ocular melanoma." (PMID 36338696, 2022). "External datasets, biospecimens, and cell lines further validated the aberrant expression and prognostic role of DLL3 in ocular melanoma." (PMID 36338696, 2022). "Results from biospecimens and cell lines further confirmed the prognostic value and expression pattern of DLL3 in ocular melanoma." (PMID 36338696, 2022). "Integrated analyses of multiple ocular melanoma datasets revealed that DLL3 was a dysregulated methylation-driven gene in UM metastasis and could serve as a biomarker to predict the prognosis of patients with UM." (PMID 36338696, 2022). "High DLL3 expression prolonged the OS of patients with ocular melanoma." (PMID 36338696, 2022). "Consistently, we also observed increased DLL3 expression in ocular melanoma cell lines." (PMID 36338696, 2022).
oncocytic adenoma (1 paper, 2025). A benign neoplasm composed of large cells with abundant eosinophilic granular cytoplasm. "We examined five parathyroid adenomas, including a lipoadenoma, a chief cell adenoma, an oncocytic adenoma, and two clear cell adenomas; all these tumors were negative for both DLL3 and SEZ6." (PMID 40699376, 2025).
pancreatic ductal adenocarcinoma (1 paper, 2023). An infiltrating adenocarcinoma that arises from the epithelial cells of the pancreas. "This is the first study that demonstrates the positive association between DLL3 expression in the tumor specimen with both progression-free and overall survival in resected pancreatic ductal adenocarcinoma patients." (PMID 37893184, 2023).
Pancreatic NECs (1 paper, 2025). "Pancreatic NECs (n = 2) showed strong DLL3 positivity (50–98% of cells) (average H-score 200), and one case had strong SEZ6 expression in 20% of the tumor cells (H-score 60)." (PMID 40699376, 2025). "DLL3 was positive in two pancreatic NECs (H-score 197), and SEZ6 was positive in 1 (H-score 60)." (PMID 40699376, 2025).
paraganglioma (1 paper, 2025). A benign or malignant neoplasm arising from paraganglia located along the sympathetic or parasympathetic nerves. "Three extra-adrenal paragangliomas had weak to moderate DLL3 positivity in 10–100% of the tumor cells (average H-score 43; range 10–100); one was metastatic, one was SDH-deficient, and the other was non-metastatic." (PMID 40699376, 2025). "Three of 20 paragangliomas expressed DLL3 weakly (H-score 43), and six expressed SEZ6 (H-score 73)." (PMID 40699376, 2025). "Paragangliomas have also been reported to express DLL3, and we confirm this finding." (PMID 40699376, 2025).
parathyroid adenomas (1 paper, 2025). "One of four parathyroid carcinomas expressed DLL3 weakly (H-score 30), and all four were negative for SEZ6; five parathyroid adenomas were negative for both." (PMID 40699376, 2025).
parathyroid carcinomas (1 paper, 2025). "Among the four parathyroid carcinomas examined, one (25%) had positivity for DLL3 with weak staining in 30% of cells (H-score 30)." (PMID 40699376, 2025). "We are the first to report DLL3 expression in PitNETs and one parathyroid carcinoma." (PMID 40699376, 2025).
prostate neuroendocrine carcinomas (1 paper, 2025). "Delta-like protein 3 (DLL3), a Notch ligand, has been identified in high-grade small- and large-cell lung carcinomas and prostate neuroendocrine carcinomas (NECs)." (PMID 40699376, 2025).
prostate tumor (1 paper, 2021). "Immunohistochemical stains of the primary prostate tumor demonstrated positive staining of the AR, NKX3.1, and PSMA, and negative staining for neuroendocrine (NE) markers synaptophysin, chromogranin A, and DLL3." (PMID 34385567, 2021).
small cell carcinoma (1 paper, 2025). A neuroendocrine carcinoma composed of small malignant cells which are often said to resemble "oat cells" under the microscope. "DLL3, a downstream effector of ASCL1 and a Notch signaling inhibitor is highly expressed in NEPC and small cell cancers." (PMID 41514539, 2025).
thymic neuroendocrine tumor (1 paper, 2025). Thymic endocrine tumor is a rare, malignant, primary thymic neoplasm originating from neuroendocrine cells, presenting as a mass within the anterior mediastinum. "Two thymic neuroendocrine tumors (NETs) had weak expression of DLL3 (H-score 20) and SEZ6 (H-score 70)." (PMID 40699376, 2025).
viral infection (1 paper, 2018). "Here, we show that silencing of DLL3 during hepatocarcinogenesis is closely related to viral infection, especially hepatitis B virus (HBV) infection (p = 0.005)." (PMID 29555949, 2018).
tumor (147 papers, 2012 to 2026). "Next, given the clear association of DLL3 positivity with high-grade disease, we aimed to explore the correlation of DLL3 tumor IHC positivity with lesion-level SSTR PET avidity." (PMID 41264896, 2025). "In medullary thyroid carcinoma (MTC), DLL3 overexpression (≥50% tumor positivity) associates with diminished overall and disease-free survival, particularly in cases exhibiting exfoliated cells, reinforcing its prognostic relevance in aggressive disease." (PMID 40496850, 2025). "Neuroendocrine neoplasms overexpress DLL3, which is linked to tumor progression and generally indicates a poor prognosis, especially in patients with NEC." (PMID 41375037, 2025). "The following sections systematically analyze DLL3’s multifaceted roles in various neoplasms, highlighting both diagnostic/prognostic utilities and therapeutic vulnerabilities." (PMID 40496850, 2025). "The strongest expression of DLL3 was observed in a recurrent sparsely granulated silent corticotroph tumor that also had loss of ATRX." (PMID 40699376, 2025). "Positive DLL3 expression (≥1% tumor cells) correlated with STK11/KEAP1 mutations (characteristic of NSCLC-like LCNEC, as STK11/LKB1 mutations are frequent in NSCLC)." (PMID 41200177, 2025). "Emerging biomarkers, such as DLL3 expression, T-cell-inflamed gene expression profiles, and blood tumor mutational burden, show promise in preliminary studies but require validation in prospective ES-SCLC cohorts." (PMID 41050648, 2025). "High DLL3 expression was reported to compromise the anti‐tumor immunity and associated with a shorter PFS in a clinical cohort with 30 SCLC patients who received chemo‐immunotherapy." (PMID 39974662, 2025). "We completed DLL3 immunohistochemistry (IHC) on 379 tumor samples from patients with GEP NENs, analyzing associations between DLL3 IHC positivity, clinicopathologic features, and outcomes." (PMID 41264896, 2025). "MTCs with DLL3 overexpression (defined as ≥ 50% of positive tumor cells) were associated with significantly lower disease-free survival (p = 0.041) and overall survival (p = 0.01)." (PMID 38958823, 2024). "DLL3 overexpression, defined as ≥ 50% of positive tumor cells, was also associated with a significantly lower disease-free survival (p = 0.041) and overall survival (p = 0.01)." (PMID 38958823, 2024). "Multivariate analysis by Cox Hazard model showed that, high DLL3 expression and maximum tumor size >5 cm were independent risk factors for PFS, where NSE < 35 ng/mL and age < 70 were independent prognostic factors for OS." (PMID 38847733, 2024). "We also looked into possible connections between DLL3 expression and levels of immune infiltration, tumor mutational burden (TMB), and microsatellite instability (MSI) in 34 different cancer types." (PMID 37179118, 2023). "Enrichment analysis revealed that DLL3-related DEGs were mainly involved in tumor- and immune-associated signaling pathway, suggesting that DLL3 is significantly involved in the tumor development process." (PMID 37274780, 2023). "In the crosstabs, there were statistically significant associations between DLL3 expression in the tumor and perineural invasion (p = 0.007) and lymph node involvement (p = 0.029)." (PMID 37893184, 2023). "After internalization, tesirine is released and causes DNA damage in tumor cells that overexpress DLL3." (PMID 37893184, 2023). "The univariate analysis for PFS confirmed that patients with high DLL3 tumor expression showed a lower risk of recurrence after surgery compared with those with low DLL3 (HR: 0.55; 95%CI: 0.34–0.87; p = 0.011)." (PMID 37893184, 2023). "As expected, an association between DLL3 expression in tumor and in stroma was confirmed (p = 0.018)." (PMID 37893184, 2023). "Delta-like ligand 3 (DLL3) represents an inhibitory ligand of the Notch receptor whose overexpression on the surface of neoplastic neuroendocrine cells is associated with tumor progression." (PMID 37509621, 2023).
tumor (continued). "Considering high- and low-grade tumors as separate groups, the high DLL3 expression was again associated with the peripheral site of the neoplasm (p = 0.01 for high-grade and p < 0.001 for low-grade tumors)." (PMID 34568063, 2021). "Differences in DLL3 expression between matched samples would suggest therapy-associated changes in the tumor cells." (PMID 34692726, 2021). "In murine models, overexpression of DLL3 was associated with cell proliferation, tumor growth and reduced apoptosis." (PMID 34513663, 2021). "Therefore, we selected this antibody combination for isolating DLL3/EpCAM/ROR1+ tumor‐associated EVs (tEV), as it provides superior performance across human samples." (PMID 40285610, 2025). "Corresponding mProtein expression was assessed using fluorescence‐labeled DLL3 antibody in DLL3/epithelial cell adhesion molecule (EpCAM)/receptor tyrosine kinase‐like orphan receptor 1 (ROR1)+ tumor‐associated EVs (tEV), captured with a mixture of DLL3, EpCAM, and ROR1 monoclonal antibodies." (PMID 40285610, 2025). "Combining with Delta‐like ligand 3 (DLL3) mRNA in exosomes and its membrane protein in extracellular vesicle‐associated with tumor may distinguish SCLC patients from high‐risk smokers." (PMID 40285610, 2025). "In addition to DLL3, the tumor mutational burden (TMB), characterized by a high number of somatic non-synonymous mutations, has recently emerged as a potential biomarker for SCLC patients." (PMID 38468968, 2024). "Additionally, the Cox univariate proportional hazard model for OS also demonstrated that high DLL3 tumor expression is related to a lower risk of death compared with those having low DLL3 expression in tumor cells (HR 0.59; 95%CI: 0.37–0.93; p = 0.024)." (PMID 37893184, 2023). "Furthermore, an interesting association was found between DLL3 tumor protein expression and PD-L2 expression (p = 0.022)." (PMID 37893184, 2023). "For example, SCLC cells express different tumor-specific markers, including Delta-like protein 3 (DLL-3), which may be associated with a worse prognosis in patients with SCLC." (PMID 37509621, 2023). "The aim of this study was to determine the protein expression levels of Notch1, Hes1,Ascl1, DLL3 in SCLC tumor specimen and the potential association of these biomarkersto platinum chemotherapy sensitivity, prognosis as well as clinical factors in SCLCpatients." (PMID 33104707, 2020). "Single-cell RNA sequencing of SCLC biopsies identifies heterogeneity in DLL3 expression, and analysis of circulating tumor cells (CTC) distinguishes individual patients as predominantly DLL3Pos or DLL3Low." (PMID 41532856, 2026). "In this trial, tumor uptake of the radiotracer—a zirconium‐89‐labeled anti‐DLL3 antibody ([89Zr]Zr‐DFO‐SC16.56)—showed high concordance with DLL3 protein expression confirmed by IHC." (PMID 41415713, 2025). "In UCEC cell lines, DLL3 expression was knocked down, resulting in a significant decrease in the proliferative and migratory capabilities of the tumor cells, consistent with the bioinformatics predictions." (PMID 40066092, 2025). "Further studies involving ALLO-213, an allogeneic DLL3 CAR-T chosen from a selection of scFv-based anti-DLL3 candidates in a subcutaneous tumor murine model, are also currently underway." (PMID 40160238, 2025). "In summary, these findings suggest that inhibition of DLL3 expression attenuates the ability of HEC-1-A tumor cells to establish pulmonary metastases." (PMID 40066092, 2025). "The largest systematic review to date reported DLL3 positivity in 80–93.5% of SCLC tumors using a threshold of ≥1% tumor cells and 58.3–91.1% with ≥25% expression." (PMID 40496850, 2025). "Engineered exosomes restored miR-508-5p, inhibited DLL3, and reduced tumor growth and metastasis in mouse models." (PMID 40066092, 2025). "Currently, the anti-tumor drugs targeting the DLL3 in SCLC mainly include antibody-drug conjugates (ADCs), bispecific T-cell engagers (BiTEs), and CAR-T cell therapy." (PMID 41415276, 2025).